VWF (von Willebrand factor)
Diseases named in the same sentence as VWF in open-access papers (continued):
Sharing a sentence is not in itself a finding about the gene and the disease.
COVID-19 (continued). "Elevated vWF antigen levels can be detected in COVID-19 cases and are recommended to help estimate the death risk." (PMID 38107577, 2023). "First, an increase in von Willebrand Factor levels is seen, and this has been associated with the development of immunothrombosis in COVID-19." (PMID 37175392, 2023). "In contrast, fibrin(ogen) and vWF deposition in lungs of COVID-19- and pancreatitis-associated SIRS/ARDS-patients was elevated in micro- and macrovessels while it was less pronounced in the microvasculature as compared to VN." (PMID 36845099, 2023). "Collectively, in the lungs, these observations suggest key pathophysiologic involvement of VWF in COVID-19–associated thrombus formation." (PMID 37333991, 2023). "Elevated vWF levels have been linked to endothelial injury, disease severity, and increased mortality in COVID-19 patients." (PMID 36992415, 2023). "COVID-19 can disrupt the endothelial system, causing a massive release of von Willebrand factor, favoring thrombosis." (PMID 35887714, 2022). "Since COVID-19 is associated with a significant increase in VWF levels, there is a relative deficiency of ADAMTS-13, resulting in large VWF multimers." (PMID 35215805, 2022). "A single-center cross-sectional study report showed that VWF activity and antigen levels continued to increase as the disease progressed, which was associated with the poor prognosis of COVID-19 patients." (PMID 35139909, 2022). "On the other hand, vWF are released into the blood stream due to the endothelial cell dysfunction caused by COVID-19." (PMID 35887770, 2022). "COVID-19 infected patients are at an increased risk of aberrant coagulation, consistent with elevated circulating levels of ultra-high molecular weight VWF multimers, D-dimer and procoagulant EVs." (PMID 36564503, 2022). "Taken together, our data demonstrate increased levels of VWF and sP-selectin are linked to the severity of lung disease in COVID-19 and correlated with biomarkers of inflammation and vascular inflammation." (PMID 35588115, 2022). "One possibility is that endothelial damage is an early event in the pathogenesis of severe COVID-19, with endothelial cells releasing VWF and sP-selectin which cause microvascular obstruction of pulmonary capillaries and decreased oxygenation." (PMID 35588115, 2022). "Deregulation of CS component 3 and C5a are associated with increased vWF antigen possibly linking vascular damage to alternative CS activation in COVID-19." (PMID 34904186, 2022). "In COVID-19-associated coagulopathy, concentrations of D-dimer, von Willebrand factor (VWF), and interleukin (IL)-6 are elevated with increasing severity of the disease, and the incidence of thrombosis is higher in severe cases." (PMID 35328761, 2022). "We also observe a decrease in CD144 expression in the lung microvasculature of COVID-19 patients that is associated with increased platelet recruitment and VWF deposition." (PMID 35709328, 2022). "The reciprocal relationship between VWF and ADAMTS13 in thrombosis is widely studied, and several groups reported that COVID-19 causes a significant increase in formation of large VWF multimers, and decrease in activity and/or levels of ADAMTS13." (PMID 36514048, 2022). "As VWF concentration in plasma is an indicator of inflammation, endothelial activation and damage, our results suggest that the association of VWF and COVID-19 severity is very likely mediated through genetic regulation." (PMID 35634344, 2022). "Von Willebrand factor indices were markedly elevated, suggesting severe COVID-19-associated coagulopathy." (PMID 35946614, 2022). "Similar to our study, inverse correlation with von Willebrand cleaving protease, ADAMTS13, and vWF antigen has consistently been associated in both hospitalised and intensive care COVID-19 patients." (PMID 34476137, 2021). "The cirrhosis-associated abnormalities of ACE, IL-6, VWF antigen, and antiplasmin parallel those observed in severe COVID-19." (PMID 34945736, 2021).
COVID-19 (continued). "Nevertheless, it would be highly useful to monitor vWF as an independent prognostic marker of severe COVID-19 and risk for respiratory distress syndrome in adults." (PMID 33787680, 2021). "Several authors reported hemostatic alterations in vWF/ADAMTS13 axis that were strongly associated with disease severity in COVID-19 patients, including increased levels of vWF accompanied by low normal or mildly decreased ADAMTS13 activity." (PMID 34834519, 2021). "We aimed to investigate the relationship between von Willebrand factor (VWF) biomarkers, intravascular hemolysis, coagulation, and organ damage in COVID-19 patients and study their association with disease severity and mortality." (PMID 33709050, 2021). "Factor D, upregulated by COVID-19 and involved in the alternative pathway, is correlated with markers of endothelial cell injury (e.g., angiotensin 2) and coagulation (e.g., vWF), possibly contributing to the association between COVID-19 and coagulopathy." (PMID 34485339, 2021). "Consistent with the fact that COVID-19 causes a widespread endotheliopathy is the evidence of marked rises in vWF." (PMID 34208470, 2021). "COVID-19-associated coagulopathy seems to happen due to excessive levels of von Willebrand factor, platelet activation, and hypercoagulability." (PMID 33585030, 2021). "Overall, peak D-dimer levels and the vWF/ADAMTS13 ratio were associated with the severity of critical illness in COVID-19 patients with hypoxic respiratory failure in an ICU setting." (PMID 34476137, 2021). "Interestingly, VWF was downregulated in cats, contrasting with its elevation in severe human COVID-19 cases, potentially indicating a reduced risk of vascular injury." (PMID 41200555, 2025). "Elevated levels of Von Willebrand Factor (VWF) have been associated to an increased need of mechanical ventilation and higher mortality risk in COVID-19 patients, but the hypothesis of a shared genetic background has not been explored." (PMID 41585277, 2025). "Consistent with this, NETs were found to correlate closely with serum von Willebrand factor (vWF) levels in COVID-19-related AKI." (PMID 41169399, 2025). "It has been reported that COVID-19 is associated with elevated levels of vWF antigen and activity, which may be linked to an increased risk of thrombosis in infected patients." (PMID 40650217, 2025). "Long-term endothelial dysfunction in patients who have recovered from COVID-19 has been associated with elevated levels of vWF, factor VIII and other procoagulant molecules, while reduced protein C activity and increased inhibitory factors further disrupt haemostatic balance." (PMID 41516301, 2025). "In addition, it was demonstrated that non-O blood groups are associated with a higher risk of thrombosis during COVID-19 due to increased levels of von Willebrand factor and Factor VIII." (PMID 38792740, 2024). "Also, von Willebrand factor (vWF), a mediator of immunothrombosis associated with endothelial inflammation, was sharply increased in COVID-19 and long COVID patients vs. controls." (PMID 38675987, 2024). "The implications of low ADAMTS13 activity in COVID-19 have also been shown in pregnancy, with an increased vWF RiCof:ADAMTS13 activity ratio being significantly associated with a higher risk of pregnancy-related complications including pre-term delivery (OR 1.9, 95% CI 1.1–3.5)." (PMID 39274365, 2024). "von Willebrand factor (vWF), crucial in hemostasis and thrombosis, bridges activated platelets and ECs and serves as a marker of endothelial damage and thrombotic risk in sepsis and other serious infectious diseases, particularly COVID-19." (PMID 38921594, 2024). "COVID-19 infection leading to acute mesenteric ischemia is presumed to be a COVID-19-associated hypercoagulable state, von Willebrand factor activation, and direct intestinal endothelial damage due to binding of SAR-CoV-2 to angiotensin-converting enzyme 2 in the intestinal cell epithelium." (PMID 38882959, 2024).
COVID-19 (continued). "Severe COVID-19 has also been associated with endothelial specific changes and effects such as elevated endothelial activation, hypercoagulability, and increased presence of von Willebrand Factor." (PMID 37938797, 2024). "•It is unclear whether VWF only marks endothelial damage or promotes COVID-19–associated coagulopathy." (PMID 37333991, 2023). "Additionally, elevated vWF:Ag activity has been linked to a greater likelihood of severe COVID-19 requiring ICU admissions and it also predicts portal hypertension and mortality in patients with liver cirrhosis." (PMID 36831088, 2023). "We were not able to show a direct association between platelet and NETosis markers in our results, despite the interaction between NETs and vWF being implicated as an important mechanism behind the platelet hyperactivation contribution to COVID-19-related thrombotic complications." (PMID 37239041, 2023). "An Austrian cross-sectional study showed that higher values of dimethylarginine, von Willebrand factor, homocysteine, and β-2-glycoprotein antibodies, and lower levels of homoarginine and tryptophan in post-COVID-19 patients were associated with microangiopathy development (p < 0.05)." (PMID 36979849, 2023). "Furthermore, a higher risk of thrombosis in COVID-19 patients was attributed to an elevated vWF level." (PMID 38203423, 2023). "Thus, several clinical studies suggested that vWF is the potential biomarker of endothelial damage and thrombotic risk in COVID-19 as extremely high levels of vWF are common in COVID-19 patients." (PMID 36982738, 2023). "Our results confirmed that severe COVID-19 is associated with vWF/ADAMTS 13 imbalance." (PMID 38069327, 2023). "In summary, we demonstrated that severe COVID-19 is associated with ADAMTS 13/vWF imbalance." (PMID 38069327, 2023). "VWF interacts with the circulatory system and platelets in hemostasis and thrombosis by sensing and responding to changes in hemodynamics, which have been associated with atherosclerosis, stroke, and more recently, COVID-19 thrombotic symptoms." (PMID 36959823, 2023). "Elegant studies have shown a significant increase in vWF antigen and its activity in patients with COVID-19, which could be a factor in the higher risk of thrombosis." (PMID 38049897, 2023). "Furthermore, the increase in the ratio of vWF antigen activity to ADAMTS13 was strongly associated with the severity of COVID-19." (PMID 36622519, 2023). "Moreover, recent findings revealed mortality to be significantly correlated with VWF antigen (r = 0.38; p = 0.0022) and soluble thrombomodulin (r = 0.38; p = 0.0078) among patients with COVID-19-associated coagulopathy." (PMID 36926331, 2023). "In addition to being a respiratory disease, COVID-19 is a ‘vascular disease’ since it causes a leaky vascular barrier and increases blood clotting by elevating von Willebrand factor (vWF) levels in the blood." (PMID 36982738, 2023). "The close association between NETs and vWF may suggest a role for NETs in COVID-19-associated vasculopathy leading to AKI." (PMID 37051234, 2023). "In addition, the levels of soluble vWF antigen and thrombomodulin were positively associated with the mortality rate of COVID-19 patients." (PMID 37092518, 2023). "Finally, we used the ROC curve to estimate a cut-off value for the diagnosis of COVID-19; LA-1 has better diagnostic accuracy than VWF (87.1% vs. 73.8%) with AUC was 0.88." (PMID 36138306, 2023). "Severe COVID-19 is associated with vWF/ADAMTS 13 imbalance, which may contribute to thrombotic complications." (PMID 38069327, 2023). "Others have shown that elevated VWF and sP-selectin levels are associated with severe COVID-19." (PMID 35588115, 2022). "In addition, in the placenta of pregnant women with severe COVID-19, higher expression of vWF was associated with lower claudin-5 and vascular endothelial (VE-cadherin) in the endothelium from decidua and chorionic villi." (PMID 35431989, 2022).
COVID-19 (continued). "Another important factor contributing to a significantly increased risk of thrombosis in patients with COVID-19 is high activity of VWF, which is released from the alpha granularity content during degranulation of previously activated platelets or from endothelial cells." (PMID 36551272, 2022). "It has been documented that COVID-19 is implicated with a multi organ microangiopathic process with endotheliopathy, vascular thrombosis, overt inflammatory cytokine response and abnormalities of von Willebrand factor-platelet axis." (PMID 35687543, 2022). "Besides the dysregulated renin angiotensin aldosterone system, it is assumed that two other mechanisms are implicated in COVID-19-associated thrombosis, namely, excess cell secretion of vWF and the activation of the innate immune response." (PMID 34073119, 2021). "While more investigation is required, emerging data suggest that COVID-19 is associated with increased consumption of HMWM VWF, which could be indicative of increased platelets aggregte formation." (PMID 34575297, 2021). "The main hypothesis of this retrospective study is that VWF biomarkers are associated with coagulation in COVID-19." (PMID 33709050, 2021). "In addition to D-dimer, there are also other coagulation markers that are dysregulated such as factor V, factor VII, factor VIII, and von Willebrand factor (VWF) in patients with COVID-19 and who are at risk for VTE." (PMID 34829418, 2021). "Interestingly, vWF significantly increases with age and in non-0 blood type individuals, both risk factors for COVID-19." (PMID 34834519, 2021). "Von Willebrand factor (VWF) was reported that it has close links to inflammation and thrombus formation, and it also associated with the mortality of COVID-19 patients, and upregulated significantly in all of the mild and severe groups compared with the healthy groups." (PMID 35095487, 2021). "Therefore, we recommend systematic measurement of vWF and aPL in all patients hospitalized for COVID-19 to estimate their risk for unfavorable evolution." (PMID 33787680, 2021). "Additionally, imbalances in von Willebrand factor (VWF) and ADAMTS13, a metalloprotease that cleaves VWF, are implicated in COVID-19-related microangiopathy." (PMID 40850218, 2025). "In fact, previous studies also showed severity of COVID-19 is associated with increased levels of inflammatory proteins (interleukin 6), coagulation proteins (VWF and fibrinogen), but a specific link with development of thromboembolic outcome could not be found." (PMID 40224277, 2025). "Additionally, non-coding variants within the ABO locus have been reported to be associated with COVID-19 severity, VWF levels, VTE risk, and a spectrum of hematological, cardiovascular, and metabolic traits, in some cases across distinct studies and phenotypic analyses." (PMID 41311061, 2025). "It has been also tested that VWF may be a marker for thrombotic risk in COVID-19." (PMID 36944974, 2023). "Our results imply that missense vWF variants might modulate the thrombotic risk in COVID-19." (PMID 36980889, 2023). "Acute COVID-19 is associated with both a hypercoagulable state and with bleeding; the resolution of the apparent paradox is temporal since the hypercoagulation can use up elements such as von Willebrand factor (VWF) that are then insufficient for normal coagulation to occur." (PMID 36043493, 2022). "The low percentage of thrombosis early in the disease is consistent with the hypothesis of gradual depletion of the protease ADAMTS-13 in COVID-19 and its deficiency late in the disease, which leads to an increase in the size and number of VWF multimers underlying thrombus formation." (PMID 35215805, 2022). "Moreover, the results indicate enhanced activation of the alternative complement pathway is most prevalent in patients with severe COVID-19 and is associated with markers of endothelial injury (i.e., angiopoietin-2) as well as hypercoagulability (i.e., thrombomodulin and von Willebrand factor)." (PMID 34446527, 2021).
COVID-19 (continued). "Evidence associating sodium toxicity with thrombosis and stroke in COVID-19 patients is grounded in research findings linking thrombosis to elevated serum sodium in mice, mediated by vascular endothelial cell secretion of the blood-clotting factor, the von Willebrand Factor (vWF)." (PMID 34440945, 2021). "Increased endothelial cell activation and Weibel–Palade body exocytosis in severe COVID-19 lead to markedly increased plasma VWF levels." (PMID 40362344, 2025). "Zhang and Bignotti noted significantly elevated plasma levels of VWF in COVID-19 patients compared to healthy controls concomitant with lower plasma ADAMTS13 activity in patients with critical COVID-19." (PMID 40362344, 2025). "In critically ill COVID-19 patients, elevated levels and activity of vWF, soluble P-selectin (a marker of endothelial and platelet activation), soluble CD40L, and factor VIII have been observed." (PMID 40002898, 2025). "COVID-19 induces a significant release of VWF from endothelial cells due to the extensive endothelial activation and damage." (PMID 40850218, 2025). "Our chromatin conformation analyses provide evidence that non-coding variants in ABO, associated with VWF levels, VTE risk, and COVID-19 severity, are in spatial proximity to ADAMTS13 in endothelial cells." (PMID 41311061, 2025). "Research has found that critical COVID-19 patients had a lower ratio of ADAMTS13/VWF activity, suggesting a potential role of both factors in disease progression." (PMID 41585277, 2025). "Evidence from thromboinflammatory conditions, including COVID-19, indicates that elevated vWF levels combined with reduced ADAMTS13 activity are associated with disease severity and thrombotic risk." (PMID 41007843, 2025). "Disruption of the vWF-ADAMTS13 axis, characterized by elevated vWF and reduced ADAMTS13 activity has been implicated in thrombotic disorders, including COVID-19-asscoiated coagulopathy, where this imbalance correlates with disease severity and mortality." (PMID 41007843, 2025). "The von Willebrand factor then becomes an attractive independent prognostic marker of severe COVID-19 and acute respiratory distress syndrome." (PMID 41585277, 2025). "Plasma levels of (VWF: Ag) and (VWF: RCo) are significantly elevated in patients with COVID-19, which correlates with poor prognosis, increased severity, and higher mortality rates." (PMID 40699808, 2025). "From the GWAS Catalog, at the ABO locus, we have identified a total of 26 variants related to VWF levels, 29 variants related to VTE, and 43 variants related to COVID-19 (A1–A3)." (PMID 41311061, 2025). "While mild to moderate reductions in ADAMTS-13 activity have been observed, possibly associated with markedly increased VWF levels, severe ADAMTS-13 deficiency appears to be rare in COVID-19." (PMID 40993743, 2025). "Hospitalized COVID-19 patients also exhibit heightened fibrinogen and vWF levels, which further promote microvascular thrombosis." (PMID 39807266, 2025). "Our findings further support the concept of COVID-19 as an endotheliopathy and highlight the potential of vWF-CBA as a readily accessible biomarker of endothelial injury and thrombotic risk." (PMID 40508203, 2025). "On the other hand, VWF levels were significantly higher in the COVID-19+ vs. post-COVID-19 group, with considerable variation in VWF levels in COVID-19+ women." (PMID 40303405, 2025). "The result of this study aligns with previous systematic reviews and meta-analyses, which found elevated vWF levels in COVID-19 patients, suggesting a link between vWF and the development of thrombosis in COVID-19 patients." (PMID 40283058, 2025). "In ICU COVID-19 patients, vWF concentration and activity were further elevated compared to non-ICU patients." (PMID 41311551, 2025). "von Willebrand factor (vWF) is upregulated in COVID-19, highlighting the role of endothelial involvement." (PMID 39102126, 2024).